MTOR (mechanistic target of rapamycin kinase)
Diseases named in the same sentence as MTOR in open-access papers (continued):
Sharing a sentence is not in itself a finding about the gene and the disease.
tumor (continued). "Previous studies have reported that miR-100 regulate the mTOR signaling pathway in a variety of tumor types." (PMID 34976182, 2022). "The Zhenwu decoction inhibited the rapid growth of the tumor by regulating crucial PI3K/Akt/mTOR molecule and prolonged survival time by improving adrenal and spleen function." (PMID 38094222, 2022). "Several studies have proven that the PI3K/AKT/mTOR pathway is a key regulatory pathway for cell growth and resistance to tumour treatment." (PMID 36294896, 2022). "The complexity of mTOR signaling in shaping anti-tumor immune responses has been extensively reviewed elsewhere, and is beyond the scope of the present review." (PMID 36077374, 2022). "In an apparent contradiction, the PI3K/mTOR axis is necessary for the induction of apoptosis after the treatment of tumor cells with IFN-α." (PMID 36552831, 2022). "Studies have disclosed that PI3K/AKT/mTOR signaling pathway is involved in the viability, differentiation, apoptosis, aging, and other processes of a variety of tumor cells." (PMID 36237584, 2022). "mTOR is a key kinase of PI3K/AKT/mTOR signaling pathway, which can regulate the tumor cell proliferation, differentiation, apoptosis and other processes." (PMID 35962453, 2022). "AKT, as a central player of PI3K/AKT/mTOR pathway, becomes an attractive anti-tumor target and a potential combo partner for PARP inhibition." (PMID 35419627, 2022). "For example, the combination of the PI3K inhibitor GDC0941 and the mTOR inhibitor everolimus was demonstrated to suppress tumor growth in a patient-derived xenograft UM model." (PMID 35804957, 2022). "mTOR inhibition has significant activity against a broad range of human cancers in vitro and in human tumor xenograft models." (PMID 35392243, 2022). "Glucose deprivation in tumor cells attenuates the glycolytic ability of T cells, leading to inhibition of the mTOR pathway." (PMID 36319992, 2022). "As it has been reported that tumor cells with PI3K/AKT/mTOR pathway activation are likely to be more sensitive to AKT inhibition, baseline PI3K/AKT/mTOR pathway activation status as assessed by PTEN IHC and pAKT IHC was evaluated." (PMID 35419627, 2022). "The results showed that KRT17 promoted tumour growth through the Akt/mTOR pathway and glucose uptake pathway." (PMID 35281081, 2022). "Upon activation of the mTOR signaling pathway, it regulates protein synthesis, gene transcription, and tumor metabolism, contributing to immune cell differentiation and regulation of proliferation." (PMID 35795855, 2022). "PTEN acts as a potent tumor suppressor within the PI3K/AKT/mTOR pathway by preventing buildup of phosphatidylinositol-3, 4, 5-triphosphate (PIP3), which promotes activation of AKT." (PMID 36039910, 2022). "For example, the phosphoinositide 3 kinase (PI3K) pathway phosphorylates Akt (protein kinase B), leading to activation of mTOR (mammalian target of rapamycin), which upregulates protein synthesis in tumor growth." (PMID 35897635, 2022). "The protein kinase B/mammalian target of rapamycin (Akt/mTOR) pathway is necessary to regulate cell proliferation and invasion, and its pathological abnormal activation is inseparable from tumor invasion and metastasis." (PMID 35309903, 2022). "Tumor cells control T cell metabolism by competing for glucose and, as a result, inhibiting T cell mTOR activity, glycolysis ability, and IFN-γ production in order to achieve immune escape." (PMID 36276846, 2022). "In one study on human OSCC, tumours with high expression of p-mTOR had lower overall survival with an independent effect noted in multivariate analysis." (PMID 35883491, 2022). "Autophagy is both a tumor suppressor pathway and a survival mechanism for tumor cells to withstand metabolic stress and resist treatment. mTOR is a critical regulator of autophagy." (PMID 36115852, 2022).
tumor (continued). "Of note, there was a good correlation between plasma and tumor genomic profiles when focusing on genes involved in the PI3K/AKT/mTOR pathway." (PMID 35122700, 2022). "The SFA-EAA diet reduced tumour growth in vivo, promoted endoplasmic reticulum (ER) stress, and inhibited mechanistic/mammalian target of rapamycin (mTOR) activity in the tumours." (PMID 35367410, 2022). "In this report, everolimus was selected as the most potent therapeutic drug among a panel of FDA-approved mTOR inhibitors and led to tumor regression in the patient diagnosed with a recurrent GBM." (PMID 35955765, 2022). "The mTOR pathway highlights targeting tumor cell proliferation, survival, and metabolism to play a critical role in tumor development, treatment resistance, and poor prognosis." (PMID 36778600, 2022). "Abnormal mTOR activation can regulate several essential features of tumor formation including aberrant cellular metabolism, cell migration and invasion, and angiogenesis." (PMID 35414770, 2022). "Abnormal activation of the PI3K/AKt/mTOR pathway is related to tumor metabolism, cell growth, invasion and migration, and angiogenesis." (PMID 35800058, 2022). "Activating the PI3K/AKT/mTOR pathway contributes to tumor development and a resistance to anticancer therapies." (PMID 36551566, 2022). "Recent investigations have observed an antitumor effect of using a LAT1 inhibitor because it suppresses the phosphoric acid of mTOR in tumor cells, inhibits its downstream cell proliferation signals, and elicits G1 arrest and apoptosis." (PMID 35177712, 2022). "The mTOR signaling system regulates gene transcription and protein manufacturing to control proliferation of cell, differentiation of immune cell, and tumor metabolism." (PMID 36293326, 2022). "Taken together, combination therapy with 8GL and an mTOR inhibitor effectively inhibited tumor growth and prolonged mouse survival." (PMID 36437247, 2022). "As a vital signaling pathway in the delivery of extracellular signals to the nucleus, PI3K/AkT/mTOR is involved in tumor cell growth, apoptosis, and proliferation." (PMID 35310040, 2022). "The synergism of mTOR and different metabolic inhibitors has been described in several tumor types, including CCRCCs, in which the combination of everolimus and GLS inhibitor (CB-839) was also tested." (PMID 36142502, 2022). "Artemisinin inhibited the proliferation of tumor cells by inhibiting the phosphorylation of Akt and S6 in mTOR signaling pathway." (PMID 35646647, 2022). "The main objective of this study is to assess the anti-tumor activity of cimetidine and vitamin C via mitigating the tumor-associated mast cell mediators in the TME and inhibiting the activation of the PI3K/AKT/mTOR trajectory." (PMID 35798765, 2022). "Contrary to our observations, studies have reported increase phosphorylation of mTOR in advance tumor stages." (PMID 35655775, 2022). "In vivo, TBs-C enhances autophagy and inhibits tumor growth by downregulating the PI3K/AKT/mTOR pathway with low toxicity." (PMID 35529455, 2022). "In terms of Hallmark in tumor, glycolysis, hypoxia and PI3K/AKT/MTOR were activated in high-risk cohort." (PMID 36686701, 2022). "The PI3K/AKT/mTOR axis is involved in tumor survival, proliferation, and distant metastasis, supporting the development of target therapies." (PMID 35887120, 2022). "The mammalian target of rapamycin (mTOR) is elevated in PCa, making this protein attractive for tumor treatment." (PMID 36139561, 2022). "Rapamycin also led to increased survival and inhibition of tumor progression and mTOR signaling in the WT livers, indicating that mTOR activation also plays a tumor-promoting role in the GS-WT tumors, which is in agreement with a previous report." (PMID 36256480, 2022).
tumor (continued). "Taken together, our study provides a connection between mTOR-dependent tumor growth and CHK1/2, highlighting the importance of CHK1/2 inhibition as a potential antitumor strategy in TSC2-deficient tumors." (PMID 35359406, 2022). "While finely tuned mTOR signaling is essential for the normal development of the CNS, GSCs instead exploit the improper activity of mTOR to fuel tumor growth and infiltration." (PMID 35328780, 2022). "Branched-chain amino acids (valine, leucine, and isoleucine; BCAAs) are essential amino acids that promote the expression of mitochondria-related genes to enhance tumor proliferation and activate the mTOR signaling pathway to stimulate tumor growth." (PMID 36553562, 2022). "PD-L1 expression in NSCLC tumor cells can be promoted by the mTOR and ERK regulatory mechanisms in activated EGFR pathways." (PMID 35992815, 2022). "The BRD4 inhibitor JQ-1 enhanced the anti-tumor activity of the mTOR inhibitor Palomid 529 in RCC cells." (PMID 35918352, 2022). "PI-103, a PI3K/mTOR inhibitor, has also been published to be related to the regulation of a variety of tumor cells." (PMID 35085103, 2022). "The Akt/mTOR signalling pathway regulates cell growth, proliferation, motility, metabolism and cell size, and inhibition of this pathway promotes tumour regression." (PMID 35016681, 2022). "Targeting the PI3K/AKT/mTOR signaling pathway as a therapeutic strategy improves MPeM tumor shrinkage." (PMID 35501851, 2022). "In this review, we focus on PI3K/AKT/mTOR inhibitors that have shown great anti-tumor potential in studies performed on xenograft models and pancreatic cell lines and inhibitors tested in clinical trials." (PMID 36077529, 2022). "Due to mTOR activation in post-transplant-associated EBV-SMT, some studies have reported the successful use of sirolimus for tumor control while simultaneously preventing transplant rejection." (PMID 35141174, 2022). "PI3K/Akt/mTOR inhibition restricts cell proliferation, migration, and survival, at the same time facilitating immune surveillance and immune-cell-dependent tumor cell killing." (PMID 35682571, 2022). "phosphatase and tensin homolog (PTEN) tumor-suppressor activity in the PI3K/Akt/mTOR pathway is essential to regulate many cellular processes of GC, including proliferation, survival, energy metabolism, and metastasis." (PMID 36505792, 2022). "The PI3K/AKT/mTOR pathway is abnormally activated in most tumour cells and mediates tumour cell growth, migration, invasion, and anti-apoptosis." (PMID 35840921, 2022). "Currently, many studies have shown that Akt/mTOR signaling promotes the Warburg effect and tumor development by increasing GLUT1 trafficking and activation of glycolytic enzymes, as well as by inducing glycolysis." (PMID 36285300, 2022). "PI3K/Akt/mTOR signaling pathway is an important pathway that regulates apoptosis and can be aberrantly activated by malignant tumor cells to exert apoptosis-inhibiting and proliferation-promoting effects in tumor cells." (PMID 36313111, 2022). "As an important intracellular signal transduction pathway, the PI3K/Akt/mTOR pathway is involved in tumor development, cellular metastasis and proliferation." (PMID 36062301, 2022). "In contrast, because the mTOR signaling pathway regulates autophagy and tumor-cell apoptosis, it can also promote tumor occurrence and progression." (PMID 36077992, 2022). "TSC2 in complex with TSC1 has tumor suppressor functions via regulation of the mechanistic target of rapamycin kinase (mTOR) signaling pathway." (PMID 35962345, 2022). "The PI3K-AKT/mTOR signaling pathway is reported to play a central role in regulating tumor cell proliferation, cell cycle, apoptosis, and movements." (PMID 35468874, 2022). "Many reports have indicated that inhibition of PI3K/Akt/mTOR signaling pathway triggers apoptosis and inhibits the proliferation of tumor cells, which have elevated Akt levels." (PMID 36506551, 2022).
tumor (continued). "Upregulation of RP S6, mTOR, and Erk1/2 correlates with a cell cycle activation, which in turn promotes tumor proliferation, infiltration, and EMT." (PMID 36552039, 2022). "Gene set enrichment analysis (GSEA)analysis indicated that high expression of CCT3 was closely correlated with tumor-related signaling pathway mTOR pathway (MTORC1/PI3K AKT mTOR) and HNSCC cell survival." (PMID 36185198, 2022). "To identify signaling pathways involved in citrate‐mediated tumor suppression in vivo, we found that administration of SCT activated MAPK and mTOR signaling pathways in HCT116 tumor cells in vivo." (PMID 34747157, 2022). "Markedly, SBI-0206965 anti-tumor effect has been evidenced in vivo as it showed potent tumor inhibition when combined with mTOR inhibitors, hence allowing it for use in the clinic." (PMID 36160153, 2022). "Previous studies have demonstrated that the inhibition of CTSK can significantly decreased the phosphorylation of mTOR at S2448 in Caki cells and reduced tumor growth and induced cell death in a xenograft model." (PMID 36005209, 2022). "Numerous studies have indicated that the cell cycle is the convergence point of the PI3K/AKT/mTOR signalling cascade and that atypical cell cycle progression is an essential feature of tumours." (PMID 35883139, 2022). "Some studies have indicated that the PI3K/AKT pathway has a specific therapeutic target for KIRC management, which produces possible values for MTOR and/or related pathway inhibitor drugs against the tumor." (PMID 35945960, 2022). "PTEN also plays a vital role as a tumour suppressor via the negative regulation of the PI3K/AKT/mTOR signalling pathway." (PMID 35877237, 2022). "The PI3K/AKT/mTOR pathway is one of the most relevant cascades activated in GBM related to tumor growth, metabolism, cell proliferation/survival, angiogenesis, autophagy, and chemotherapy resistance." (PMID 35562862, 2022). "Mice were classified into study and control groups (n = 8 per group) for treatment with placebo control or the combination of AKT and mTOR inhibitors for 21 days, which resulted in a significant reduction in tumor growth (p = 0.0068) in the treatment group." (PMID 35454789, 2022). "Everolimus is a mechanistic/mammalian target of rapamycin (mTOR) inhibitor used to prevent tumor growth by inhibiting the PI3K signaling pathway." (PMID 35506423, 2022). "On the other hand, amino acid deprivation in tumor cells promotes autophagy and cell survival via the mTOR pathway." (PMID 36618350, 2022). "Since the AKT/mTOR signaling pathway plays an important role in tumor progression, the regulatory role of CPSF7 on this pathway was analyzed." (PMID 36349192, 2022). "Taken together, these results indicate that knockdown of Peg3 significantly block hyperactive mTOR-mediated HCC tumor progress and migration." (PMID 36451866, 2022). "Emerging evidence suggests that Akt/mTOR signalling pathway affect tumour cells function, including cell proliferation, apoptosis, cell cycle, invasion, autophagy and angiogenesis." (PMID 35315581, 2022). "Due to genetic mutations (PI3KCA, PTEN depletion, and receptor tyrosine kinase activation, etc), Akt-mTOR cascade is frequently hyper-activated in OS, contributing to tumor initiation and disease progression." (PMID 35115496, 2022). "When tumor epithelial cells are deprived of amino acids, mTOR repression rewires metabolism to use amino acids to form the degradation of ECM proteins in favor of the starved cells." (PMID 35163745, 2022). "It is considered that the PI3K/Akt/mTOR cascade serves as a major antiproliferative signaling pathway responsible for magnolol-induced tumor growth inhibition." (PMID 36234977, 2022). "The PI3K/AKT/mTOR pathway was assessed to reveal the signaling mechanisms by which the TAMC mediators support tumor growth and survival." (PMID 35798765, 2022).
tumor (continued). "In fact, tumours are also characterized by the hyperactivation of the mTOR signalling pathway, leading to increased cell proliferation and invasiveness." (PMID 35955882, 2022). "The MAPK and mTOR signaling pathway are most important signaling cascade and play key role in the proliferation and migration of tumor cells." (PMID 36506551, 2022). "Since autophagy confer stress tolerance to mantain tumor cell survival upon PI3K-AKT/mTOR inhibitors treatment we next tested if CQ was able to potentiate the antitumor effect of both ipatasertib and taselisib in TNBC MDAMB231 and MDAMB468 cells." (PMID 35761360, 2022). "Some proteins can affect the radioresistance and chemoresistance of tumor cells by regulating the PI3K/Akt/mTOR pathway." (PMID 35392233, 2022). "Activation of Akt, mTOR and Wnt/β-catenin pathways attenuated the anti-tumor property of HCG22 in OSCC cells." (PMID 35525925, 2022). "Specifically, CLs exhibited downregulation of many membrane receptors and ECM molecules participating in the activation of the PI3K/Akt/mTOR pathway, while their expression in tumours varied." (PMID 36220861, 2022). "In the Cox regression multivariate analysis, IL-7R, mTOR, and tumour stage were the strongest predictors of survival." (PMID 35778432, 2022). "mTOR inhibitors can reduce TSC tumor growth and seizure frequency, and preclinical FCD studies indicate seizure suppression." (PMID 35587487, 2022). "A significant reduction in the levels of c-Myc, PDHK1, and LDHA as well as the phosphorylation of PI3K, AKT, mTOR, and p70S6K in tumor tissues, inhibiting c-Myc-mediated metabolic reprogramming have been reported." (PMID 36438836, 2022). "mTOR inhibitors (e.g., sirolimus) inhibit signaling in the phosphoinositide 3 kinase (PI3K) – Akt-mTOR pathway, which plays a key role in tumor growth and lipid metabolism." (PMID 35548413, 2022). "Immune-related gene PDK1 is able to manipulate PD-L1 level in tumor tissue by mTOR signaling, and further affects the immune escape of tumor." (PMID 36245844, 2022). "Our analysis showed that the mutation frequency of MTOR in MSI-H patients was significantly increased compared with MSS patients, which can affect the protein activity of mTOR and influence the tumor response to rapamycin treatment." (PMID 35883111, 2022). "Loss of HIF-1α in NK cells blocks tumor growth and hypoxia upregulation of HIF-1α in NK cells is dependent on PI3K/mTOR signaling pathway activation in response to cytokine receptor gamma chain, reducing NK cells tumor suppressive function." (PMID 35211123, 2022). "This mTOR-mediated compartmentalized metabolism directly influences the acquisition of multiple aggressive tumor hallmarks." (PMID 36589241, 2022). "BCAAs are building blocks for proteins and also stimulates mTOR signaling pathway to promote tumor growth." (PMID 35785192, 2022). "The PI3K/AKT/mTOR pathway not only plays a vital role in physiologically cell biology but has also been identified as a growing target for tumor therapy." (PMID 35812733, 2022). "In parallel studies, prevention or clearance of radiation-induced senescence with senostatic agents targeting the mTOR pathway or a senolytic agent was capable of mitigating radiation-enhanced tumor growth." (PMID 35158337, 2022). "Modulating the tumor-extrinsic activities of mTOR signaling has also been known to determine the antitumor response induced by anti-PD-1 therapy." (PMID 35831271, 2022). "HSP90B1 downregulation mediated the PI3K/AKT/mTOR pathway to inhibit tumor growth in vitro and in vivo." (PMID 36452480, 2022). "For example, the expression of PD-L1 and B7-H3 (also known as CD276) in tumor cells can stimulate aerobic glycolysis in tumor cells by activating the PI3K/AKT/mTOR pathway." (PMID 36034789, 2022). "Some previous studies had reported that PI3K/mTOR signaling pathway played a critical regulatory role in the tumor microenvironment." (PMID 36091162, 2022).